ASB4 (ankyrin repeat and SOCS box containing 4)
Description:
Probable substrate-recognition component of a SCF-like ECS (Elongin-Cullin-SOCS-box protein) E3 ubiquitin-protein ligase complex which mediates the ubiquitination and subsequent proteasomal degradation of target proteins. Promotes differentiation and maturation of the vascular lineage by an oxygen-dependent mechanism (By similarity). Also acts as a negative regulator of GPS1, a component of the COP9 signalosome (CSN) multiprotein complex, thereby inhibiting the serine phosphorylation of IRS1 (By similarity). Regulates IRS4 levels by directing its degradation via ubiquitination and thereby decreases the downstream signal of IRS4. Plays a critical role during early vascular development and proper placentation. Mechanistically, negatively regulates the transcriptional regulator inhibitor of DNA binding 2/ID2 expression through polyubiquitination and proteasome dependent degradation.
Synonyms: ASB-4
Tractability: No criterion of Open Targets' tractability assessment is met for any kind of drug.
Gene: Protein-coding gene on chromosome 7 (95,478,444 to 95,540,233, forward strand). Ensembl gene ENSG00000005981.
Subcellular location: Cytoplasm
Pathways (Reactome):
Immune System: Antigen processing: Ubiquitination & Proteasome degradation
Metabolism of proteins: Neddylation
Gene Ontology:
Molecular function: ubiquitin protein ligase binding; ubiquitin-protein transferase activity
Biological process: positive regulation of vasculogenesis; protein autoubiquitination; intracellular signal transduction; protein ubiquitination
Cellular component: Cul2-RING ubiquitin ligase complex; Cul5-RING ubiquitin ligase complex; cytoplasm; cytosol
Genetic constraint (gnomAD): Loss-of-function variants: 30 observed, 33.19 expected, observed/expected ratio (o/e) 0.9, 90% interval 0.68 to 1.23. The upper end of that interval is the gene's LOEUF score, 1.23, which puts it in group 5 of 6, group 1 being the genes least tolerant of losing a copy. Missense variants: 509 observed, 504.93 expected, observed/expected ratio (o/e) 1.01, 90% interval 0.94 to 1.09. Synonymous variants: 184 observed, 196.84 expected, observed/expected ratio (o/e) 0.93, 90% interval 0.83 to 1.06.
Homologues: Orthologues: chimpanzee ASB4 (99% identical), macaque ASB4 (99% identical), guinea pig ASB4 (96% identical), rabbit ASB4 (96% identical), dog ASB4 (96% identical), mouse Asb4 (92% identical), rat Asb4 (92% identical), pig ASB4 (85% identical), tropical clawed frog asb4 (69% identical), zebrafish asb4 (58% identical). Paralogues in human: ASB18 (35% identical), ASB10 (32% identical), ASB16 (31% identical), ASB14 (23% identical), ASB15 (20% identical), ASB3 (20% identical), MPHOSPH8 (17% identical).
Diseases named in the same sentence as ASB4 in open-access papers:
ASB4 is named in the same sentence as 17 diseases in open-access papers, as found by Europe PMC text mining. Sharing a sentence is not in itself a finding about the gene and the disease. The quoted sentences say what the papers report.
Hypertension (5 papers, 2014 to 2025). The presence of chronic increased pressure in the systemic arterial system. "ASB4-deficient mice phenocopy human pre-eclampsia, including hypertension and proteinuria in late-stage pregnant females, indicating that ASB4 mediates vascular differentiation in the placenta through the degradation of ID2." (PMID 27030794, 2016). "ASB4 mediates vascular differentiation in the placenta by degrading ID2, and deletion of Asb4 in mice induces a pathology that phenocopies human pre-eclampsia, including hypertension and proteinuria." (PMID 40410732, 2025). "ASB4-null mice display a full spectrum of preeclampsia-like phenotypes during pregnancy including hypertension, proteinuria, and decreased litter size." (PMID 39201703, 2024). "ASB4-null female mice develop a full spectrum of phenotypes of preeclampsia during late-stage pregnancy including hypertension, proteinuria, and decreased litter size." (PMID 39201703, 2024). "Asb4−/− mice on normal chow (NC) develop mild preeclampsia-like phenotypes during pregnancy, including hypertension, proteinuria, and reduced litter size." (PMID 36768469, 2023). "Lastly, pregnant Asb4−/− mice exhibited symptoms consistent with pre-eclampsia, including proteinuria and hypertension." (PMID 24586788, 2014). "Lastly, deletion of Asb4 in mice induces a pathology that phenocopies human pre-eclampsia, including hypertension and proteinuria in late-stage pregnant females." (PMID 24586788, 2014).
Obesity (3 papers, 2023 to 2025). Accumulation of substantial excess body fat. "Genome-wide association studies have identified the link between single nucleotide polymorphisms (SNPs) in the ASB4 gene and obesity." (PMID 39201703, 2024). "Variants in the ASB4 gene have been associated with obesity in humans, and a functional connection between the ASB4 gene and obesity has been established in mice." (PMID 39201703, 2024). "Additionally, the association between variants of the ASB4 locus and obesity has been identified in humans." (PMID 36768469, 2023). "High-fat diet (HFD)-induced obesity aggravates preeclampsia-like phenotypes in ASB4-null female mice." (PMID 39201703, 2024). "This review discusses the connections between preeclampsia, obesity, and ASB4." (PMID 39201703, 2024). "NF-κB can initiate the inflammation cascade through the activation of macrophages, and this could be a new angle to examine the mechanistic relationships between ASB4 and obesity." (PMID 39201703, 2024). "Disruption in the ASB4-miRNA interaction could possibly play a role in the development of obesity and its related metabolic changes." (PMID 39201703, 2024). "ASB4’s involvement in cancer cell lines might also provide potential links with obesity." (PMID 39201703, 2024). "Future research could aim to elucidate the precise mechanisms linking obesity-related metabolic dysregulations with preeclampsia pathogenesis, as well as to explore novel targets such as ASB4 that could potentially mitigate the impact of maternal obesity on pregnancy outcomes." (PMID 39201703, 2024). "In mice, POMC-specific ASB4 knockdown resulted in impaired glucose tolerance without obesity, while overexpressing ASB4 in POMC neurons caused an increase in food intake without obesity." (PMID 39201703, 2024). "HFD-induced obesity markedly worsens the preeclampsia-like phenotypes in the absence of ASB4." (PMID 36768469, 2023). "We investigated how obesity influences preeclampsia in mice lacking ankyrin-repeat-and-SOCS-box-containing-protein 4 (ASB4), which promotes trophoblast differentiation via degrading the inhibitor of DNA-binding protein 2 (ID2)." (PMID 36768469, 2023).
preeclampsia (2 papers, 2023 to 2024). Preeclampsia is a hypertensive disorder of pregnancy that is characterized by new-onset hypertension with proteinuria presenting after 20 weeks of gestation, and depending on mild or severe forms may initially present with severe headache, visual disturbances, and hyperreflexia. "Future studies must, therefore, include whether neuronal glucose regulation also contributes to the exaggerated insulin increase in the maternal circulation during pregnancy and whether the genetic variants of ASB4 influence preeclampsia." (PMID 36768469, 2023). "Regardless, variants of ASB4 as well as those in other protein degradation mechanisms that control ID2 levels during trophoblast differentiation require further attention as risk factors for preeclampsia." (PMID 36768469, 2023). "Asb4−/− female mice develop mild preeclampsia-like phenotypes during pregnancy, including increased systolic blood pressure (SBP) and urinary albumin excretion, as well as a decreased litter size." (PMID 39201703, 2024). "A previous study showed that a subset of trophoblasts remains undifferentiated with sustained high ID2 expression in the placenta of Asb4−/− dams and that this plays a role in preeclampsia." (PMID 36768469, 2023). "In the following sections, we will discuss the role of insulin and leptin in preeclampsia as these factors are altered in the obese mouse model of preeclampsia—i.e., feeding ASB4-null mice with a high-fat diet (HFD), as described in the last section of this review." (PMID 39201703, 2024). "Previously, we reported that Asb4−/− dams had lower circulating VEGF levels than WT dams, and we and others proposed that lower VEGF levels contribute to preeclampsia-like symptoms in pregnant mice." (PMID 36768469, 2023). "Here, by feeding an HFD or regular normal chow (NC) to Asb4−/− females before and through the entire pregnancy, we demonstrate that HFD-induced maternal obesity significantly worsens all the preeclampsia-like phenotypes in Asb4−/− dams." (PMID 36768469, 2023). "In this review, we discuss the potential roles of altered metabolic factors on preeclampsia pathogenesis in obese mice lacking ASB4." (PMID 39201703, 2024). "Furthermore, maternal obesity induced by a high-fat diet aggravates preeclampsia-like phenotypes in pregnant mice lacking ASB4." (PMID 39201703, 2024). "In this study, we test our hypothesis that the adverse effects of maternal obesity on preeclampsia start early at the trophoblast differentiation stage, using a mouse model of preeclampsia lacking ankiryn-repeat-and-suppressor of cytokine signaling (SOCS)-box-containing-protein 4 (ASB4)." (PMID 36768469, 2023). "Although this treatment regimen does not affect pregnancy in WT mice, pregnant mice lacking ASB4 with hyperinsulinemia show increased placental ID2 and decreased plasma VEGF and develop more severe preeclampsia-like phenotypes." (PMID 36768469, 2023). "While ASB4 is unlikely to be the sole molecule involved in the ID2 degradation process, its complete absence delays and impairs the placental differentiation process, leading to preeclampsia." (PMID 36768469, 2023).
acute lower respiratory infection (1 paper, 2022). "Both ASB4 and CDC42BPA showed an association with COPD with acute lower respiratory infection." (PMID 36194576, 2022).
autism (1 paper, 2022). Persistent deficits in social interaction and communication and interaction as well as a markedly restricted repertoire of activity and interest as well as repetitive patterns of behavior. "LRFN2 knockout mice exhibited autism-like behavioural abnormalities and, similar to SHANK2 and ASB4, could be relevant in terms of pig feeding related behaviors." (PMID 36057580, 2022).
colorectal cancer (1 paper, 2025). A primary or metastatic malignant neoplasm that affects the colon or rectum. "The peptide epitope of ASB4, which is not expressed in healthy tissues, causes a CTL response that destroys colorectal cancer CSCs while preserving non-CSCs." (PMID 40097979, 2025).
hepatocellular carcinoma (1 paper, 2024). A malignant tumor that arises from hepatocytes. "In liver cancer, ASB4 expression is upregulated by microRNA-200a (miRNA-200a), and suppressing ASB4 mitigated the invasion and migration ability of a subset of hepatocellular carcinoma cells." (PMID 39201703, 2024).
Hyperinsulinemia (1 paper, 2023). An increased concentration of insulin in the blood. "Consistent with in vitro data, in vivo data show that ID2 expression increases in the placentas from obese dams lacking ASB4 with hyperinsulinemia." (PMID 36768469, 2023).
lung carcinoma (1 paper, 2022). "Other COPD- hub genes (CDC42BPA, ASB4, DPF3 and TMEM67) are were also associated with lung function related traits and lung cancer." (PMID 36194576, 2022). "Additional COPD hub genes like SREK1, TMEM67, CDC42BPA, DPF3, and ASB4 were identified as prognostic markers in lung cancer, which is reported in 1% of COPD patients." (PMID 36194576, 2022). "In PhenoScanner, 6 out of 12 hub genes (IRAK2, MECOM, ASB4, CDC42BPA, DPF3 and TMEM67) have revealed an association with lung related traits and lung cancer." (PMID 36194576, 2022). "Interestingly, we have also identified that the expression status of other COPD hub genes like SREK1, TMEM67, CDC42BPA, DPF3, and ASB4 improves the survival duration of lung cancer patients, hence they may act as potential molecular drug targets and/or biomarkers for both COPD and/or lung cancer." (PMID 36194576, 2022).
placental disease (1 paper, 2014). "Together, these findings indicate that ASB4 regulates TB cell differentiation into placental vasculature through the degradation of ID2 and that loss of Asb4 in the developing placenta contributes to placental disease." (PMID 24586788, 2014). "Together, these results suggest that Asb4−/− mice phenocopy human pre-eclampsia and may serve as a model for both early placental vascularization and human placental disease." (PMID 24586788, 2014).
type 2 diabetes (1 paper, 2024). "In human subjects with type 2 diabetes, ASB4 expression is reduced in the hypothalamus, suggesting the potential role of ASB4 in satiety and glucose homeostasis." (PMID 39201703, 2024).
tumor (1 paper, 2019). "Recently a new antigen, Ankyrin repeat and SOCS box protein 4 (ASB4), was described as target molecule of CTLs recognizing CSCs/CICs and not the differentiated cellular components of the tumor." (PMID 31758404, 2019).
ASB4 also shares sentences with these, for which no sentence is quoted: asthma (1 paper); cancer (1); Impaired glucose tolerance (1); liver cancer (1); lung disease (1).